BRCA1 (BRCA1 DNA repair associated)
Diseases named in the same sentence as BRCA1 in open-access papers (continued):
Sharing a sentence is not in itself a finding about the gene and the disease.
cancer (continued). "In addition to loss-of-function mutations in BRCA1/2 and other HR genes, expression of these genes can also be lost in cancers through DNA hypermethylation and other mechanisms." (PMID 39007266, 2024). "ATM, BRCA2, and BRCA1 mutations have been well characterized in breast, ovarian, and other cancers." (PMID 39132489, 2024). "One previous study showed that PARPis treatment in BRCA1-deficient tumors could stimulate an immune response against cancer cells by activating the STING pathway." (PMID 38236558, 2024). "Given the increased cancer risk in BRCA1 mutation carriers, optimizing Zn and Cu levels through dietary and active interventions could provide a preventive strategy." (PMID 39061909, 2024). "While mutations in BRCA1/2 and other HR genes are useful biomarkers for PARPi therapy, it has become increasingly clear that many other common oncogenic events can also alter the PARPi sensitivity of cancer cells." (PMID 39007266, 2024). "The molecular insight into how BRCA1 mutations can lead to cancer development is still unknown, but the high conservation of BRCT sequences in mammals highlights their functional significance." (PMID 38543119, 2024). "However, the dependence of BRCA1 deficient cancer cells on PARP1 S-phase activity predicts that loss of this activity such as by targeting FANCJ will be a therapeutic option." (PMID 38521768, 2024). "Our results highlight that the PARPi synthetic lethality phenotype observed in ATM-deficient cancer cells may be regulated through the subsequent loss of BRCA1/2." (PMID 38807759, 2024). "It is worth noting that the negative impact is not universal, and some individuals may only experience short-term distress following the revelation of BRCA1/2 carrier status and cancer risk management, cancer prevention, and cancer treatment(s)." (PMID 39050256, 2024). "Germline genetic testing for hereditary breast and ovarian cancer (HBOC) enables targeted treatment and risk management interventions for women who carry pathogenic or likely pathogenic (P/LP) variants in a cancer predisposition gene, such as BRCA1, BRCA2 or PALB2." (PMID 39766065, 2024). "Both these cancers, while distinct in their manifestation and impact on different genders, share common ground in the molecular dysregulation of cellular processes, including DNA repair pathways and common mutation in genes such as BRCA1/2." (PMID 38750579, 2024). "Furthermore, the generation of resistance through the reactivation of HR through mutations or epigenetic regulation of BRCA1, and other "BRCAness'' genes is a significant challenge in PARPi therapy that has been observed in diverse cancers." (PMID 38993666, 2024). "This review explores the intricate relationship between cancer, Dox-induced cytotoxicity, autophagy modulation, and the potential implications of autophagy in DNA damage repair pathways, particularly in the context of BRCA1/2 mutations." (PMID 39199310, 2024). "Numerous phase III studies demonstrate the efficacy of PARP inhibitors in BRCA1/2-mutated cancer." (PMID 38730642, 2024). "The importance of the 53BP1 pathway extends to BRCA1-mutated cancers." (PMID 39227718, 2024). "If confirmed, the evaluation of zinc levels and the levels of other microelements in the blood of BRCA1 carriers may be used as a marker of the presence of early cancers and as a risk factor for later cancer development." (PMID 38790714, 2024). "Objective responses were observed only in BRCA1/2 mutation carriers with BRCA-associated cancers." (PMID 38938274, 2024). "Several studies have investigated whether an enrichment for mutations affecting other genes would be detected in BRCA1 or BRCA2 cancers and provide a basis for the synthetic viable interactions." (PMID 39198848, 2024). "Consequently, PARP inhibitors have emerged as a focal point in the therapeutic targeting of cancers harboring BRCA1/2 mutations, leveraging the dependency of these cancer cells on PARP1-mediated repair pathways." (PMID 39051184, 2024).
cancer (continued). "Furthermore, higher levels of GLUT1 expression were observed in cancer cells carrying germline mutations in the BRCA1 gene." (PMID 38745772, 2024). "For BRCA1, 10 different variants in association of cancer were identified in 17 individuals." (PMID 39148954, 2024). "Moreover, our data highlight that RAD18 is required for PCNA monoubiquitination upon HU treatment as detected by immunoblotting, consistent with our finding that PCNA ubiquitination at the K164 residue promotes fork recovery in BRCA1-deficient cancer cells." (PMID 38943334, 2024). "BRCA1 mutation carriers have an actual greater cancer risk than BRCA2 mutation carriers." (PMID 39192282, 2024). "Women may be at high risk due to a family history of cancer or a pathogenic or likely pathogenic variant in a cancer-susceptibility gene (such as BRCA1, BRCA2, or PALB2)." (PMID 38611036, 2024). "It’s noteworthy that BRCA1/2 functions as tumor suppressor genes involved in DNA repair, and mutations in these genes may predispose individuals to various human cancers." (PMID 38966174, 2024). "Basically, it is uncertain whether the defective activity of BRCA1 Δ11 splicing isoforms has a role in cancer predisposition." (PMID 39062754, 2024). "This would be particularly true in BRCA1/2 mutation carriers who develop cancer at a younger age as compared to sporadic cancer cases, thus possibly increasing their fear of having another cancer at a young age." (PMID 39192282, 2024). "This cohort study conducted at a single-institution academic national comprehensive cancer center included 172 women identified from a prospectively maintained database who had pathogenic BRCA1/2 variants and were treated with breast-conserving therapy from January 1, 1977, to December 31, 2021." (PMID 38916888, 2024). "This supported that both high and low levels of BRCA1 methylation could be associated with HRD scarring in multiple cancer types, including OV, BC and UCEC, and could indicate a history of HRD." (PMID 39055334, 2024). "The primary model for cancer development linked to BRCA1 mutations is based on the “two-hit” hypothesis, where one allele is lost, and the other undergoes a loss-of-function mutation." (PMID 39061909, 2024). "Alternatively, treating these patients with other chemo therapeutic agents such as HU, for which BRCA1/BARD1 E3-deficient cells are still sensitive might open a therapeutic opportunity for cancer treatment." (PMID 38769345, 2024). "Additionally, CRISPR-based gene editing can be used to repair genetic mutations that cause cancer, such as in the case of inherited forms of cancer caused by BRCA1 and BRCA2 mutations." (PMID 38195537, 2024). "Consequently, agnostic studies utilizing PARPis for the treatment of BRCA1/2-mutated cancers demonstrated lower response rates than breast, ovarian, prostate, or pancreatic clinical trials." (PMID 38612902, 2024). "The international comparison of insurance coverage and genetic counseling practices further highlights the importance of addressing the financial aspect of BRCA1/2 mutation testing, as access to such tests is a critical factor in early cancer detection and proper management." (PMID 38791944, 2024). "Concerningly for carriers higher fimbrial HIF-1α may also reflect synergy with BRCA1 loss as a potential cancer-driving mechanism." (PMID 38539519, 2024). "Additionally, the risks of developing various cancers, such as salpinx, peritoneum, endometrium, pancreas, prostate, and colorectum, increased in BRCA1/2 mutation carriers compared to the average population in many studies." (PMID 39590130, 2024).
cancer (continued). "Mosaic BRCA1 epimutations are observed at similar variant allele frequency (VEF) when detected in healthy women subsequently diagnosed with an incident TNBC or HGSOC many years later or detected in cancer patients after diagnosis." (PMID 40225940, 2024). "The risks of other cancers are also elevated in BRCA1-, BRCA2-, and ATM-variant carriers." (PMID 38929805, 2024). "The synthetic lethal relationship between RAD52 and BRCA1/2 supports the notion that there may be therapeutic opportunities to specifically inhibit RAD52 in homologous-recombination-deficient cancer cells." (PMID 38658755, 2024). "Notably, the potency of various clinical PARPis in trapping PARP1/2 correlates with their efficacy in killing BRCA1/2-deficient cancer cells, suggesting that PARPi induces DNA damage by trapping PARP1/2 on DNA." (PMID 39007266, 2024). "This will require pre-clinical and clinical research to understand the effect of HRR mutations, beyond BRCA1/2, in the context of each type of cancer as the impact may differ." (PMID 38882441, 2024). "Some cancer types show a significant association with mutations in well‐known cancer predisposing genes, that is, ovarian cancer in BRCA1/2, whereas new associations were revealed, such as loss of function mutations in BUB1B in lung cancer and in SDHA in melanoma." (PMID 39118233, 2024). "Cumulative exposure to cyclical periods of relatively lower NK cell tumor cytotoxicity, across the reproductive lifecycle of a BRCA1 mutation carrier, may in turn have functional relevance from a cancer predisposition perspective." (PMID 38539519, 2024). "Several studies have attempted to predict the cancer risks associated with unclassified BRCA1 missense variants by performing bioinformatics analyses based on multiple sequence alignment data and protein structure predictions as well as clinical and family history data for some of these mutations." (PMID 38543119, 2024). "Hence, we correlated blood levels of molybdenum and cancer risks on BRCA1 mutation carriers in Poland." (PMID 39300540, 2024). "Of the 556 BRCA PV carriers identified in the 11,482 cancer patients, 331(59.5%) were the carriers for the three founder variants, including 24 (4.3%) carriers of BRCA1 c.2037delinsCC, 58 (10.4%) carriers of BRCA1 c.3331_3334del, and 249 (44.8%) carriers of BRCA2 c.156_157insAlu." (PMID 38671360, 2024). "Although poly ADP-ribose polymerase (PARP) inhibitors are currently an approved treatment option for malignant tumors linked to BRCA1/2 pathogenic variants, the therapeutic potential of PARP inhibitors in NSCLC remains unclear." (PMID 38715777, 2024). "However, in cancer cells deficient in DNA repair due to BRCA1/2 mutations, PARP inhibitors cause excessive DNA damage leading to cell death." (PMID 38638566, 2024). "BOADICEA may be used to aid personalised cancer risk management and decision-making for BRCA1 and BRCA2 PV carriers." (PMID 38834293, 2024). "Consequently, BRCAness (similar to BRCA1 or BRCA2 gene mutation signatures) in cancer cells has been established to be associated with the inactivation of Pin1, which is essential for PARP inhibitor treatment, as it sensitizes cells." (PMID 39624096, 2024). "We also aimed to determine whether the RAD18/UBC13-dependent pathway of fork recovery could be targeted to modulate viability and/or drug sensitivity in BRCA1-deficient cancer cells." (PMID 38943334, 2024). "In addition to BRCA1/2, several other high-risk cancer susceptibility genes have been previously found." (PMID 39272813, 2024). "Identifying targetable aberrances in BRCA1 mutation carriers, such as sex hormones, or adopting mechanisms aimed at enhancing tumor immunosurveillance may facilitate the reduction of early cancer-promoting events." (PMID 38539519, 2024). "Q6 Does having a BRCA1 mutation affect the treatment of cancer?" (PMID 38872284, 2024).
cancer (continued). "Further, since promoter hypermethylation is the epigenetic mechanism most often associated with cancer biology in general and BRCA1 transcriptional activity in particular, here, we will use the term BRCA1 epimutation synonymously to BRCA1 promoter hypermethylation." (PMID 40225940, 2024). "However, the data show different proportions of BRCA1/2 reversal mutations in different cancer patients, and further validation is needed in a larger base of samples." (PMID 39318358, 2024). "We also observed an additive effect of HU and UBC13i, suggesting that the UBC13-dependent fork recovery pathway might be targeted to preferentially sensitize BRCA1-deficient cancer cells to replication stress inducers." (PMID 38943334, 2024). "BRCA1, a cancer susceptibility gene crucial for cell cycle regulation and DNA repair, undergoes mutations that disrupt its structure and contributing to genomic instability, transforming cells into cancer-initiating cells (CSCs)." (PMID 38543119, 2024). "Further understanding of the underlying mechanisms of cancer development among BRCA1 carriers may provide valuable insights into modifiable determinants and prevention strategies." (PMID 39061909, 2024). "It seems to be important in women at genetic risk (BRCA1 carriers) for cancers." (PMID 39061909, 2024). "However, male carriers of BRCA1/2 mutations carry a significant burden of cancer risk, which is comparable to female carriers." (PMID 39590130, 2024). "Our data indicate that the role of RAD18 in fork recovery, in addition to its proposed function in ssDNA gap filling, could also be relevant for survival in BRCA1-deficient cancer cells." (PMID 38943334, 2024). "However, the pathogenic variants of BRCA1/2 or other forms of HRD make cancer cells particularly sensitive to PARPi, the mechanism is called synthetic lethality, and the concurrent loss of both repair pathways leads to cell death." (PMID 38409030, 2024). "The localization of BRCA1 is a crucial aspect of its biology, as studies have shown that cytoplasmic localization is associated with a loss of tumor suppressor activity and an increase in the invasiveness of cancer cells." (PMID 39062754, 2024). "Indeed, BRCA1-deficient cancer patients with low hCCAR2 protein levels had lower survival rates than those with higher hCCAR2 levels." (PMID 38172598, 2024). "Due to the higher breast tissue density typically observed in younger women, mammography may be less effective as a screening strategy for detecting BRCA1/2-associated cancers, which often occur at younger ages." (PMID 39421188, 2024). "This delayed risk window may suggest an interaction between BRCA1 and a pregnancy cycle that results in initiation of new cancers, in addition to the promotion of existing, subclinical tumors." (PMID 38639936, 2024). "In addition, more efforts should be encouraged on further categorizing the pathogenicity of VUS, such as the recurrent BRCA2 c.8971 C > T in the cancer cohort and the potential splicing abnormalities causing BRCA1 c.548-15G > A in the healthy group." (PMID 38566028, 2024). "Beyond BRCA1/2, some monoallelic germline variants within the FA family may increase cancer susceptibility." (PMID 39516637, 2024). "Overall, BRCA2 has been associated with a more heterogeneous cancer spectrum, compared with BRCA1." (PMID 38339330, 2024). "A high zinc/copper (Zn/Cu) ratio could reduce cancer risk in this same population, suggesting the importance of optimizing these minerals for cancer prevention in BRCA1 carriers." (PMID 39275213, 2024). "Therefore, the BRCA1 mutation, c.2566 T > C, reduced the energy consumption of cancer cells and promoted to proliferation." (PMID 38509102, 2024). "Compared to BRCA1/2 wild-type tumors, BRCA1/2 mutation-associated cancers are more immunogenic." (PMID 39430759, 2024). "Specifically, a technique known as CRISPR/Cas9 could be used to correct BRCA1 mutations in human cells and this could serve as an initial basis for cancer therapy." (PMID 39281673, 2024).
cancer (continued). "However, we and other groups have shown that some variants of BRCA1 have the moderate HR deficiency and sensitivity to olaparib, and present an intermediate cancer risk." (PMID 38589490, 2024). "Cancer cells and cells with BRCA1/2 variants are characterized by genomic instability: they exhibit copy number modifications and numerous somatic changes in the genome, including single-nucleotide polymorphisms and structural aberrancies (structural variants, SVs)." (PMID 38397209, 2024). "The corresponding cumulative BC risks for Singapore residents from the same birth cohort, where the underlying population cancer incidences are higher compared to Malaysia, were higher, varying by ancestry group between 57 and 61% for BRCA1, and between 43 and 47% for BRCA2 carriers." (PMID 38333895, 2024). "Lowering molybdenum levels may potentially reduce cancer risk in this population, and high molybdenum levels could serve as a marker for considering preventive oophorectomy in BRCA1 carriers." (PMID 39300540, 2024). "Additionally, we assessed the allele frequencies of the genes in the gnomAD non-cancer cohort (n = 134 187), which showed significant differences in BRCA1, BRCA2, CHEK2, MUTYH, MSH6, POLE, and ERCC3 genes in comparison to our non-HBOC groups." (PMID 39148954, 2024). "Notably, patients harboring VUS demonstrated elevated cancer worry scores across the study phases in contrast to those with BRCA1 and BRCA2 pathogenic variants or wild-type counterparts." (PMID 38500651, 2024). "The results suggest that BOADICEA may be used to aid personalised cancer risk management and decision-making for BRCA1 and BRCA2 PV carriers." (PMID 38834293, 2024). "In comparison to other European populations, Slavic populations are characterized by a high percent of founder mutations, primarily in the BRCA1/2 genes, which are largely distributed in Poland, Belarus, Ukraine, and Russia, but also in other cancer susceptibility genes." (PMID 39684352, 2024). "However, cancer cells with defective homologous recombination, like those with BRCA1/2 mutations, undergo apoptosis." (PMID 38730642, 2024). "Future work in the field must lead to an understanding of exactly when and how the BRCA1 epimutations occur and, most importantly, whether primary constitutional epimutations in genes other than BRCA1 may cause an elevated risk of other cancer types." (PMID 40225940, 2024). "In case there is a significant methylation concordance for BRCA1 (and potentially other cancer risk genes as well) in monozygotic twins, current models for genetic contribution to disease risk will turn out to be overestimates and would have to be revised based on epigenetic knowledge." (PMID 40225940, 2024). "Consequently, DNPH inhibitor (DNPHi) preferentially kills BRCA1-deficient cancer cells and overcomes their PARPi resistance." (PMID 39007266, 2024). "Genomic alterations in BRCA1/2 have been highly associated with HRD in many cancers." (PMID 37173992, 2023). "Therefore, PARP1 is one of the most intensively investigated targets for treating cancers associated with BRCA1/2 deficiency." (PMID 36838818, 2023). "Interestingly, patients with BRCA1/2 mutations have different disease risks and progression patterns in two other hormonally driven cancers: ovarian and breast." (PMID 37025481, 2023). "Moreover, the expression of cancer-related BRCA1 missense variants significantly decrease yeast DNA-damage-induced HR, suggesting a functional interaction between yeast DNA repair and BRCA1." (PMID 37514027, 2023). "In our study, we investigated how socio-demographic, medical, psychological factors, risk perception, personal and/or family history of cancer, and psychological distress can impact adherence to genetic testing for BRCA1 and 2 gene mutation years after a previous cancer diagnosis." (PMID 37723374, 2023).